NRG4 (neuregulin 4)
Diseases named in the same sentence as NRG4 in open-access papers (continued):
Sharing a sentence is not in itself a finding about the gene and the disease.
Obesity (continued). "Our study revealed that irisin, FGF21 and NRG4 levels of two groups with metabolically healthy and unhealthy obesity, which were matched in terms of age, gender, BMI, fat, muscle, lean body mass, fat, and muscle distribution were similar to each other." (PMID 39008201, 2024). "NRG4 is a hormone secreted from brown adipose tissue that regulates energy metabolism in people with obesity and is thought to prevent the development of metabolic disorders." (PMID 39008201, 2024). "The expression levels of NRG4 in adipose tissues are obviously decreased in both rodent and human obesity and negatively correlated with the liver fat content." (PMID 39872218, 2024). "Obesity, a condition characterized by chronic low-grade inflammation, negatively impacts the capacity of brown and white adipocytes to express Nrg4 in humans." (PMID 39519269, 2024). "Nrg4 was initially identified as a brown fat–enriched endocrine factor that improves insulin resistance and hepatic steatosis during diet-induced obesity." (PMID 38015639, 2024). "Other elegant observational studies have also associated low Nrg4 levels with NAFLD or coronary artery disease, and subclinical atherosclerosis in adults with obesity and MetS." (PMID 39162358, 2024). "Another attractive target is neuregulin (Nrg4), a growth factor secreted by AT that regulates lipogenesis in the liver and is reduced in obesity." (PMID 37108631, 2023). "Through this research, we aim to partially explain the specific mechanisms of Nrg4 in metabolic balance and provide novel insights into obesity treatment." (PMID 37060105, 2023). "Nrg4 dampens hepatic lipogenic signaling and maintains glucose and lipid homeostasis in the context of obesity." (PMID 38136166, 2023). "Researchers have reported an association between decreased Nrg-4 levels and T2DM mellitus, obesity, insulin resistance (IR) and hyperglycemia." (PMID 36915073, 2023). "Recent work has demonstrated that neuregulin 4 (Nrg4), a brown fat-enriched adipokine, rectifies diet-induced obesity and fatty liver by alleviating hepatic lipogenic signaling." (PMID 38010450, 2023). "Central administration of recombinant Nrg4 protein (rNrg4) reduces obesity and related metabolic disorders by influencing energy expenditure and intake." (PMID 37060105, 2023). "As the PVN plays a key role in obesity and related metabolic syndrome, the findings suggest that Nrg4‐ErbB4 regulates obesity partially via hypothalamic PVN." (PMID 37060105, 2023). "This work highlights central Nrg4‐ErbB4 signaling as a potential therapeutic strategy for the treatment of obesity and related diseases." (PMID 37060105, 2023). "Collectively, our findings highlight central Nrg4‐ErbB4 signaling as a potential therapeutic strategy for the treatment of obesity and related diseases." (PMID 37060105, 2023). "Conversely, high-fat-fed mice inhibited adipogenesis due to overexpression of Nrg-4, thereby preventing high-fat diet-induced obesity and fatty liver, and improving insulin sensitivity." (PMID 36915073, 2023). "These adipokines have been characterized as exhibiting effects that can ameliorate metabolic dysregulation in obesity, suggesting that Nrg4 overexpression can further contribute to the normalization of the adipokine profile." (PMID 36703934, 2022). "Anthropometric and clinical characteristics according to obesity and correlations between serum NRG4 and these parameters." (PMID 36187779, 2022). "Neuregulin 4 (NRG4) is a novel brown-adipose-tissue-secreted adipokine with beneficial metabolic effects on obesity and its metabolic complications." (PMID 35056647, 2022). "Adipose tissue Nrg4 mRNA expression level has been demonstrated to be decreased in both mice and humans with obesity, suggesting a possible obesity-protective role." (PMID 36703934, 2022). "Other investigations reported increased levels of NRG4 in patients with type 2 diabetes, altered glucose tolerance or obesity." (PMID 36187779, 2022).
Obesity (continued). "Nrg4 has been demonstrated to improve obesity and related metabolic disorders by increasing adipose tissue angiogenesis as a pro-angiogenic factor." (PMID 36703934, 2022). "Serum Nrg4 levels in adolescent girls with obesity and PCOS were significantly downregulated by a 1-year weight intervention, which remarkably improved clinical symptoms." (PMID 36703934, 2022). "Previous evidence proved that NRG4 has been involved in several disorders related to obesity and GDM." (PMID 36072413, 2022). "Nrg4 is a newly identified adipokine and play a role in obesity, diabetes, non-alcoholic fatty liver disease (NAFLD), and CVD in human subjects." (PMID 34017266, 2021). "For instance, it was reported that Nrg4 enhances angiogenesis in adipose tissue, preventing hypoxia and inflammation in obesity." (PMID 34884763, 2021). "We investigated the effects of three different exercise training protocols on Nrg4 levels and cardiometabolic and body composition variables in sedentary men with obesity." (PMID 35197860, 2021). "Obesity was the biggest factor affecting NRG4 secretion in PCOS patients, and weight management was the key factor to solve metabolic abnormalities and fertility problems related to PCOS." (PMID 34427289, 2021). "Neuregulin 4 (Nrg4) is an adipokine that is sensitive to energy expenditure and with a potential role in metabolic homeostasis and obesity." (PMID 35197860, 2021). "Expression of NRG4 is significantly higher in brown adipose tissues and expression of NRG4 in adipose tissues is inversely related with obesity in mice and human adipose tissue." (PMID 32175323, 2020). "Decreased production of NRG4 in obesity is likely due to direct impact of pro-inflammatory cytokines produced in obesity such as TNF-α and IL-1β." (PMID 32175323, 2020). "In this regard, NRG-4 expression is reduced in WAT in obesity, both in mouse models and humans, and adiposity negatively correlates with NRG-4 expression in WAT, but not in BAT." (PMID 32655416, 2020). "In contrast, NRG-4 transgenic mice show enhanced whole body glucose metabolism and, consequently, reduced obesity and insulin resistance compared to control animals." (PMID 32655416, 2020). "More recently, the role of NRG-4 in adipose tissue vascularization was explored since the pathological adipose tissue expansion that occurs in obesity is often accompanied by a reduction in blood vessels, thereby leading to hypoxia." (PMID 32655416, 2020). "In other words, although expression of Nrg4 in one unit adipose tissue decreases in obesity, the total fat mass should rise in obese subjects, which would increase the overall expression of Nrg4 through the whole body." (PMID 31815951, 2019). "Neuregulin 4 (Nrg4) has been proposed to play a role in the pathogeneses of obesity, insulin resistance, and dyslipidemia." (PMID 29721105, 2018). "To address this, we first examined adipose tissue expression of Nrg4 in high-fat diet (HFD) induced obesity." (PMID 28752050, 2017). "We examined the correlation of adipose Nrg4 expression with obesity in a cohort of diet-induced obese mice and investigated the upstream signals that regulate Nrg4 expression." (PMID 28752050, 2017). "We previously demonstrated that fat-specific transgenic expression of Nrg4 in adipose tissue ameliorates diet-induced obesity and metabolic disorders." (PMID 28752050, 2017). "In future studies it would be interesting to focus especially on the role of Nrg4 in the prevention HF-induced obesity by propionate." (PMID 28733671, 2017). "The profile of Nrg4 expression was remarkably similar to that of adiponectin, which has been shown to decrease in eWAT during obesity." (PMID 28752050, 2017). "This current study was designed to assess the preventive and therapeutic effects of NRG4 overexpression on high fat diet (HFD)-induced obesity." (PMID 27184920, 2016).
Obesity (continued). "Previous studies have indicated that adipose tissue Nrg4 expression was reduced in obesity and negatively correlated with body fat mass in humans, but the association of circulating Nrg4 with body fat mass has been not yet studied." (PMID 27772531, 2016). "In the current study, we used a gene transfer system to enhance NRG4 expression and investigated its potential to prevent and to provide therapeutic benefits to animals with diet-induced obesity and metabolic disorders." (PMID 27184920, 2016). "To test the effect of NRG4 increase on diet-induced obesity, we overexpress NRG4 by performing hydrodynamic gene delivery." (PMID 27184920, 2016). "As a brown fat-enriched endocrine factor, Nrg4 attenuates hepatic lipogenic signaling and preserves glucose and lipid homeostasis in obesity." (PMID 27772531, 2016). "The role of Nrg4 in obesity and whole-body energy homeostasis is gradually becoming clearer." (PMID 40243151, 2025). "Furthermore, overexpressing NRG4 through hydrodynamic gene delivery significantly reduces diet-induced obesity in mice, demonstrating NRG4’s therapeutic potential and contribution to cardiovascular disease reduction." (PMID 40149686, 2025). "Consequently, our study stands out as one of the rare studies demonstrating that Nrg4 levels are higher in children with obesity compared to their normal-weight counterparts." (PMID 40283014, 2025). "Similarly, in individuals with high BMI, the mRNA expression levels of hepatic ERBB4 and NRG4 are reduced, suggesting a protective role for Nrg4-ErbB4 signaling against obesity." (PMID 40243151, 2025). "Additionally, ROC analysis revealed a direct relationship between Nrg4 and obesity, suggesting a potential role of this marker in the diagnosis of obesity." (PMID 40283014, 2025). "Besides, circulating Nrg4 levels are lower in individuals with obesity, MASLD, and T2DM, compared to healthy controls." (PMID 40243151, 2025). "Clinically, lower circulating levels of Nrg4 are negatively correlated with body mass index (BMI), waist circumference, and the presence of metabolic syndrome, supporting its potential role as both a biomarker and therapeutic target in obesity treatment." (PMID 40426925, 2025). "Serum Nrg4 levels displayed a significantly high AUC value of 0.68 and 0.74 for detecting increased carotid intima-media thickness (CIMT) and atherosclerotic plaque in patients with obesity and high risk of subclinical cardiovascular disease." (PMID 39162358, 2024). "Current clinical evidence emphasizes that the circulating levels of Nrg4 are decreased in morbid obesity, and it also highlights that Nrg4 May serve as a potential prognostic biomarker for obesity-related metabolic diseases." (PMID 39162358, 2024). "Finally, recombinant NRG4-Fc fusion protein promotes beige fat induction and improves metabolic parameters in mice with diet-induced obesity." (PMID 38015639, 2024). "Thus, measuring the levels of circulating adipokines like Nrg4 remains crucial to unveil their role in the development and progression of obesity to MetS." (PMID 39162358, 2024). "However, cumulative studies have reported that Nrg4 levels are decreased during obesity, with an emerging body of evidence demonstrating its potential use as a biomarker for metabolic diseases." (PMID 39162358, 2024). "Furthermore, treatment with recombinant NRG4-Fc fusion protein promotes beige fat induction in iWAT and improves metabolic health in mice with diet-induced obesity." (PMID 38015639, 2024). "Although abnormal circulating levels of Nrg4 are common in obesity, it remains elusive whether low or elevated levels of this batokine are associated with the onset of metabolic diseases." (PMID 39162358, 2024). "It has been documented in reviews that, evidence from preclinical studies suggests that Nrg4 may have protective effects in some metabolic disorders such as obesity, NAFLD, and T2DM." (PMID 39036605, 2024).
Obesity (continued). "Our study aims to compare the serum levels of bone morphogenetic protein 1 (BMP1), neuregulin 4 (NRG4), and apolipoprotein A5 (ApoA5) in obese and non-obese individuals and investigate their association with obesity." (PMID 39280566, 2024). "It was found that circulating Nrg4 levels play an utmost important role in the pathogenesis of NAFLD preceded by increased adiposity and insulin resistance, as well as identifying children with obesity at high risk for NAFLD." (PMID 39162358, 2024). "Thus, this systematic review aimed to elucidate the potential role of circulating levels of Nrg4 as a biomarker for the severity of obesity, GDM, T2DM, NAFLD, and CVD." (PMID 39162358, 2024). "Their results showed that Nrg4 upregulation could enhance the efficiency of ADMSCs in reducing IR and other obesity-related metabolic disorders, mainly by suppressing inflammation, enhancing glucose uptake in AT and muscle, and attenuating hepatic lipogenesis." (PMID 37108631, 2023). "However, further research is needed to determine the precise correlation between Nrg4 concentration and obesity phenotype." (PMID 38136166, 2023). "In addition, recent data show that the expression of NRG4 is significantly down-regulated in mice and human obesity." (PMID 36983737, 2023). "PVN Oxt is a critical mediator of the anti‐obesity effects of Nrg4." (PMID 37060105, 2023). "Another study examined the effects of three different training modalities, high-intensity interval training (HIIT), circuit resistance training (CRT), and moderate-intensity continuous training (MICT), on serum Nrg4 levels and various metabolic-related parameters in men with obesity." (PMID 36703934, 2022). "In the present study, we aimed to investigate the potential relationship between circulating NRG4 and obesity-associated metabolic disturbances in non-diabetic subjects with a wide range of adiposity." (PMID 36187779, 2022). "Since obesity is characterized by chronic inflammatory infiltration of adipose tissue, pro-inflammatory signaling may similarly contribute to the reduced Nrg4 expression of adipose tissue in obesity." (PMID 36703934, 2022). "Nrg4 improves metabolic dysregulation in various metabolic diseases such as insulin resistance, obesity, non-alcoholic fatty liver disease, and diabetes through several mechanisms such as anti-inflammation, autophagy regulation, pro-angiogenesis, and lipid metabolism normalization." (PMID 36703934, 2022). "The beneficial metabolic effects of Nrg4 were observed to be eliminated by anti-angiogenic drug treatment in another study, suggesting that the angiogenic effect of Nrg4 was an essential strategy in preventing obesity." (PMID 36703934, 2022). "Nrg4 is downregulated in AT during rodent and human obesity." (PMID 34831295, 2021). "The adipokine Neuregulin 4 (Nrg4) protects against obesity-induced insulin resistance." (PMID 34884763, 2021). "Recently, Nrg4 has been postulated as an adipokine with endocrine effects whose expression in adipocytes is reduced under conditions of insulin resistance such as those related to obesity." (PMID 34884763, 2021). "Nrg4 reduces obesity in mice and humans who are also exposed to various metabolic diseases." (PMID 35197860, 2021). "Moreover, Nrg4 knockout mice show an accentuated obesity-related phenotype with a high expression of proinflammatory adipokines in WAT and liver." (PMID 34884763, 2021). "Furthermore, the impact of adipose tissue NRG4 on human obesity and insulin sensitivity was also evaluated." (PMID 30766490, 2019). "However, additional studies will be necessary to clarify the relationship between human adipose tissue NRG4 and obesity." (PMID 30766490, 2019). "Wang showed that Nrg4 overexpression could improve the efficacy of mesenchymal stem cells (ADSCs) in ameliorating IR and other obesity-related metabolic disorders." (PMID 31815951, 2019).
Obesity (continued). "Wang reported that Nrg4 might activate the ErbB3/ErbB4 signaling in mice hepatocytes to coordinate glucose and lipid homeostasis in obesity." (PMID 31815951, 2019). "Thus, BMP8b and NRG4 can be considered as interconnected regulators of neuro-vascular remodeling in AT and are potential therapeutic targets in obesity." (PMID 30478315, 2018). "Taken together, these previous observations suggest that plasma Nrg4 concentration might be a useful biomarker of obesity-related metabolic and cardiovascular disorders." (PMID 29721105, 2018). "Several previous studies demonstrated that Nrg4 overexpression could attenuate obesity-induced IR in animal models." (PMID 29721105, 2018). "Thus, the reduction of plasma Nrg4 concentration is likely a consequence of augmented proinflammatory cytokine signaling in obesity." (PMID 29721105, 2018). "As a novel endocrine factor, circulating Nrg4 may activate the receptor kinases ErbB3 and ErbB4 and coordinate glucose and lipid homeostasis in obesity." (PMID 27772531, 2016). "Neuregulin 4 (Nrg4) has been identified as a new secreted adipokine that may protect against development of obesity and metabolic disorders." (PMID 27819316, 2016). "The preventive effect of NRG4 on HFD-induced obesity has been clearly demonstrated." (PMID 27184920, 2016). "Therefore, suppression of lipogenesis by NRG4 plays, at least in part, an important role in preventing diet-induced obesity." (PMID 27184920, 2016). "Given the connection between obesity-associated metabolic disorder and risk of CVD, circulating Nrg4 might be a candidate marker of CVD risk." (PMID 27819316, 2016). "Therefore, by targeting the hepatic PPARγ pathway, NRG4 protects against obesity-induced hepatic steatosis." (PMID 27184920, 2016). "Furthermore, it has been stated that Nrg4 may improve obesity by modulating the process of angiogenesis in adipose tissue." (PMID 40283014, 2025). "Peripheral neuregulin-4 stimulated neurons in the paraventricular nucleus of the hypothalamus via ErbB4 while overexpression of ErbB4 in the paraventricular nucleus has a protective effect against obesity, which supports our current hypothesis." (PMID 37373801, 2023). "The reduced hypothalamic pErbB4 in obesity may be due to the decreased Nrg4 secreted by adipocytes." (PMID 37060105, 2023). "We found that the path from adiposity and MetS was protectively mediated Nrg4 but adversely mediated by adipsin, suggesting that elevating circulating Nrg4 levels and inhibiting adipsin secreting might be therapeutic potentials for protecting obesity from MetS." (PMID 34017266, 2021). "Therefore, the purpose of this study was to examine the effects of moderate-intensity continuous training, circuit resistance training, and high-intensity interval training on Nrg4 levels, cardiometabolic, and body composition parameters in sedentary males with obesity." (PMID 35197860, 2021). "Importantly, our results confirm a possible interaction between Nrg4 and obesity, and suggest a positive effect of exercise training on obesity and lipid profiles that may be mediated by Nrg4." (PMID 35197860, 2021). "Hence, NRG-4 and adiponectin expression change in a similar manner, while NRG-4 overexpression counteracts the expression of proinflammatory cytokines involved in obesity-induced adipose tissue inflammation, such as tumor necrosis factor α (TNFα) and interleukin 1β (IL1β)." (PMID 32655416, 2020). "Therefore, the reduction in NRG-4 expression that is observed in obesity could be a consequence of the low-grade chronic inflammatory signaling present in WAT." (PMID 32655416, 2020). "Interestingly, NRG-4 overexpression promotes a healthier adipokine profile during obesity." (PMID 32655416, 2020). "Thus the eventual expressing direction of Nrg4 for the whole body in obesity would be determined by the interaction of these two opposite notions, and each of the three different results might be reasonable." (PMID 31815951, 2019).